IL4 (interleukin 4)
Diseases named in the same sentence as IL4 in open-access papers (continued):
Sharing a sentence is not in itself a finding about the gene and the disease.
Sepsis (continued). "In our previous study, we also indicated that eight functional polymorphisms (IL1B-1470, IL1B-511, IL1B-31, IL4-589, IL6-572, IL8-251, IL10-819, and TNFA-308) could be combined together to predict the risk of sepsis and organ dysfunction after trauma." (PMID 33281864, 2020). "In addition, the adoptive transfer of miR-223 over-expressed macrophages with IL-4 pre-conditioning attenuated LPS-induced sepsis mouse model." (PMID 32658933, 2020). "Because of the potent anti-inflammatory property and the resistance against LPS induced macrophage-conversion of miR-223 over-expression, IL-4 stimulated miR-223 over-expressed macrophages were tested in LPS injection mouse model as a proof of concept for sepsis treatment." (PMID 32658933, 2020). "However, the protein and mRNA levels of IL-4 gradually increased with the development of sepsis, and higher levels were noted at 72 h than at 24 h and 48 h post CLP surgery." (PMID 30881224, 2019). "The increased IL-10 and IL-4 anti-inflammatory cytokines expression corroborates to other previous authors, these cytokines contributes to decreased mortality rate in endotoxemia or sepsis." (PMID 31191818, 2019). "This sepsis-induced immunosuppressive state may be further mediated by the release of anti-inflammatory cytokines (e.g., IL-4 and IL-10)." (PMID 30885252, 2019). "We first characterized PAXgene samples of 20 sepsis patients and ten healthy controls with respect to expression of the “immunosuppressive” miRNA signature and mRNA-levels of anti-inflammatory IL4, IL10, TGF-ß and pro-inflammatory “master cytokine” interleukin 1 beta (IL-1β)." (PMID 30332984, 2018). "We found that, in a previous study, exogenous Cit alleviated the release of proinflammatory cytokines (TNF-α, IL-1β, and IL-6) in early sepsis and increased the release of late-stage anti-inflammatory cytokines (IL-4 and IL-10) to alleviate the inflammatory response of septic rats." (PMID 30498752, 2018). "Moreover, sepsis-surviving Rag1−/− mice showed similar levels of IL-4 and IL-13 in the lungs as those found in sepsis-surviving WT mice." (PMID 28374774, 2017). "Also, increased production of IL-4 and IL-13, as well as M2 polarization, is maintained in sepsis-surviving Rag1−/−mice." (PMID 28374774, 2017). "Secretion of M-CSF in IL-4&GM-CSF differentiated MO was elevated in animals surviving sepsis." (PMID 28507543, 2017). "Similar to findings obtained with sepsis-surviving Il1rl1−/− mice, the production of IL-4 and IL-13 was markedly reduced in the lungs of Stat6−/− mice on day 15 after CLP, indicating that these type 2 cytokines can induce their synthesis in a positive feedback loop in an STAT6-dependent manner." (PMID 28374774, 2017). "With regard to IL-4, it is known to play an important role in the pathogenesis of sepsis, but its precise function during the course of the disease remains unknown." (PMID 29257842, 2017). "Although there are several studies suggesting that IL-4 plays an important role in the pathogenesis of sepsis, its real role in the course of the disease remains unknown." (PMID 25614712, 2014). "Early T-cell cytokine-production capacities of the antiinflammatory cytokines, IL-4 and IL-10, were also lower in sepsis patients as a whole compared with healthy controls (2.9 (0.7 to 5) versus 8.2 (3 to 10) pg/ml; P = 0.03; and 23 (6 to 41) versus 68 (26 to 126) pg/ml, P = 0.02), respectively." (PMID 25005517, 2014). "Furthermore, the later stages of sepsis are characterized by immunosuppressant interleukins such as IL-10 and IL-4." (PMID 25399401, 2014). "However, protective as well as detrimental effects of IL-4 were described in Staphylococcus aureus-triggered murine sepsis, which appeared to depend on the host's genetic background." (PMID 23853427, 2013). "While all these studies indicate that IL-4 plays an important role in the pathogenesis of sepsis, its precise role during the course of disease remains unknown." (PMID 23853427, 2013).
Sepsis (continued). "In post-septic patients, the ratio of IFN-γ to IL-4 producing peripheral blood CD4+ T cells appears skewed towards IL-4, and the maintenance of TH1 T cells following sepsis appears to be negatively affected by a unique susceptibility to apoptosis and activation-induced cell death." (PMID 21655295, 2011). "However, available evidence suggests that IL-4 is more closely associated with Gram-positive bacteremia than with sepsis caused by Gram-negative bacteria or fungi." (PMID 41301767, 2025). "The absence of significant differences between SIRS and Sepsis_A groups suggests that IL-4 alone may have limited diagnostic value in distinguishing sepsis from non-infectious SIRS." (PMID 41301767, 2025). "Moreover, sepsis-related anti-inflammatory cytokines primarily include IL-4, IL-10, and IL-37." (PMID 40718494, 2025). "According to previous research, narcolepsy patients tend to secrete higher levels of cytokines, including IL-2, tumor necrosis factor, IL-4, and IL-13, which could be the reason for narcolepsy being a protective factor against severe sepsis and 28-day mortality in sepsis patients." (PMID 38343642, 2024). "In our study, the opposing causal relationship of 5-Hydroxyindole sulfate with IL-4 suggests that it does not act as a mediator, and its role in reducing sepsis risk may depend on other factors." (PMID 39205680, 2024). "However, in this study, IL-2 and IL-4 levels were in normal range, so the increase in IL-6 may be a predictor of KD combined with severe sepsis." (PMID 37234775, 2023). "Thus, it is possible that increased CXCR4 expression during sepsis may amplify this pathway and result in enhanced IL-2, IL-4, and/or IL-10 secretion." (PMID 29232699, 2017). "Recently, it was suggested that IL-4 promoter polymorphisms might affect the balance between the TH1 and TH2 immune response, and thereby predispose trauma patients to the development of sepsis." (PMID 23853427, 2013). "In humans, IL-4 and IL-10 levels rise during the recovery phase of SIRS and sepsis, although they typically remain lower than pro-inflammatory cytokines such as IL-6 and TNF-α." (PMID 40584120, 2025). "Elevated systemic IL-4 levels have also been documented in humans with SIRS and sepsis, as well as in bitches with pyometra, highlighting its potential anti-inflammatory role in the pathophysiology of these conditions." (PMID 40584120, 2025). "In the context of sepsis, NRP-1 has been shown to stabilize regulatory T cells (TReg), promoting the release of immunomodulatory cytokines such as IL-4, IL-10, and TGF-β." (PMID 40733612, 2025). "In conclusion, a higher IL-2/IL-4 ratio on day +7 was an early predictor of aGVHD post-HSCT, even with sepsis or ES." (PMID 40718494, 2025). "Activation of iNKT cells by α-Galcer leads to an upregulation of IFN-γ production and a concomitant downregulation of IL-4 secretion in Cecal ligation and puncture (CLP) -induced sepsis." (PMID 39720538, 2024). "Next, to confirm that the IL4 signaling pathway does not play a substantial role in the protection conferred by α-GalCer against sepsis, we employed AS1517499, an inhibitor of the STAT6 transcription factor that is critical for IL4 signaling." (PMID 39355237, 2024). "As expected, IL-4, IL-6, IL-10, IL-17, TNF-α, and CCL2 were significantly elevated from the early stage of sepsis, but on CLP day 6, all cytokines were reduced to levels similar to those of sham mice." (PMID 38385073, 2024). "In humans, MDSCs from patients with sepsis significantly suppress the ability of healthy control T cells to produce IFN-γ and IL-4 cytokines." (PMID 38609858, 2024). "IL-10 (interleukin-10), IL-4 (interleukin-4), and TGF-β (tumor growth factor beta) are the three best described anti-inflammatory regulators operating in sepsis." (PMID 37627293, 2023).
Sepsis (continued). "Using specific ELISA parameters, we analyzed the levels of porcine CRP, haptoglobin, IL-4, IL-10, PGE2, TGF-ß and porcine alpha-1 acid glycoprotein, as we considered these to be fundamental sepsis biomarkers according to existing clinical research." (PMID 38087374, 2023). "The anti-inflammatory effects of MSCs on host tissues by their secretion of TGF-β, IL-10, IL-4, and prostaglandin E2 have been reported in preclinical models of ARDS and sepsis." (PMID 33514427, 2021). "• How do cytokines (IL-1RA, IL-4, IL-10, and TGF-β) with known anti-inflammatory effects contribute to the resolution of sepsis?" (PMID 32676795, 2020). "The findings showed that sepsis resulted in decreases in blood and para-aortic lymph node CD4+ T-cell percentages, whereas percentages of interleukin (IL)-4- and IL-17-expressing CD4+ T cells were upregulated." (PMID 32290120, 2020). "A cytokine array found that the QX1 formula attenuated sepsis-induced upregulated levels of serum IFN-γ, IL-1β, IL-3, IL-6, IL-17, IL-4, IL-10, and TNF-α." (PMID 32908632, 2020). "Central treatment with BoxA improved the abnormal response of CD4+ T cells in sepsis by enhancing the expression of IFN-γ and decreasing that of IL-4, following an increase in the ratio IFN-γ/IL-4." (PMID 30881224, 2019). "Protein and mRNA expression of IFN-γ was significantly lower in the sepsis group than that in the sham group, while IL-4 expression was enhanced under septic challenge, along with lower ratio of IFN-γ to IL-4 when compared to that in the sham controls." (PMID 30881224, 2019). "Levels of plasma IFN-γ, IL-4 and IL-10 in blood serum collected upon enrolment in healthy control, ICU control and severe sepsis patients were measured." (PMID 30813927, 2019). "Transcripts of TH2-cytokines interleukin 4 (IL-4) and interleukin 10 (IL-10) as well as Treg-differentiation promoting transforming growth factor beta (TGF-β) were markedly increased in sepsis samples." (PMID 30332984, 2018). "Consistent with previous studies, IL-6 was significantly upregulated in the plasma samples from sepsis patients, as well as in the BAL fluid samples, while minimal and insignificant detection of IL-2 and IL-4 was observed." (PMID 28287491, 2017). "We found that sepsis Arrb2 TG mice were immunosuppressive, characterized by reduced pro-inflammatory (TNF-α, INF-γ) and increased anti-inflammatory (IL-10, IL-4) cytokines expression." (PMID 28525390, 2017). "Further, among other inflammatory cytokines, IL-4 has been described to rise in BALF over the course of ARDS progression, particularly in the setting of sepsis." (PMID 26919714, 2016). "In the present study we demonstrated that mice with disruption of Atg7 in T cells exhibited a reduced cytokine production of IL-2, IFN-γ, IL-4, IL-10 and IL-17 by CD4+ T cells after sepsis, compared to septic wild-type mice." (PMID 25029098, 2014). "However, recent research on the pathophysiologic mechanisms underlying sepsis indicates that the profound proinflammatory response is counteracted by certain anti-inflammatory cytokines, including IL-10, transforming growth factor (TGF-β), and IL-4, which attempt to restore immunological balance." (PMID 25614712, 2014). "The presence of interleukin (IL)‐2, IL‐4, IL‐5, IL‐6, IL‐8, IL‐10, TNF‐α and interferon‐γ was significantly more evident in all three cell culture media transfected with plasma from sepsis patients than in controls, indicating that the transfected cells potentially underwent necroptosis." (PMID 40318009, 2025). "In contrast, the severe group showed enrichment in pro-inflammatory and immune-activating pathways such as PI3K, IL8, IL-4, IL-13, ERK, and VEGF signaling play key roles in acute and chronic inflammation, contributing to diseases such as meningitis, pneumonia, sepsis, and urinary tract infections." (PMID 41417796, 2025).
Sepsis (continued). "Studies analyzing proinflammatory cytokines, such as IL-8, IL-12, IL-17A, and IL-18, and anti-inflammatory cytokines, such as IL-4, IL-10, and IL-11, have reported no effective neutralizing antibodies to improve the outcomes of human sepsis." (PMID 40136690, 2025). "Specifically, IL-4 levels were higher only in Sepsis_D patients (p = 0.0153) but not in Sepsis_A patients (p = 0.2590)." (PMID 41301767, 2025). "In a CLP surgery-induced sepsis model of mice, the administration of 5–20 g/kg of the QX1 decoction reduced sepsis-induced upregulated levels of serum IFN-γ, IL-1β, IL-3, IL-6, IL-17, IL-4, IL-10 and TNF-α." (PMID 39051370, 2024). "Since α-GalCer pretreatment increased the IL4-producing iNKT2 cell subset, we reasoned that OCH pretreatment may confer similar or more enhanced protective effects against sepsis than α-GalCer." (PMID 39355237, 2024). "Similar negative associations were observed for AXIN1 (OR = 0.715, CI = 0.517–0.990), FGF-23 (OR = 0.783, CI = 0.624–0.981), IL-4 (OR = 0.772, CI = 0.608–0.980), and OSM (OR = 0.755, CI = 0.592–0.962), whereas IL-2 showed a positive correlation with sepsis (OR = 1.320, CI = 1.008–1.729)." (PMID 39205680, 2024). "We found that neither the frequency nor the number of basophils producing IL4 in the spleen and liver were increased, implying that IL4-producing immune cells such as CD4+ T cells and basophils are not essential for mediating the protective effects of α-GalCer pretreatment against sepsis." (PMID 39355237, 2024). "Treatment with a STAT6 inhibitor was unable to modulate disease progression, indicating that IL4 signaling did not significantly affect iNKT cell-mediated protection against sepsis." (PMID 39355237, 2024). "On the basis of its favourable (and myeloid-specific) uptake in haematopoietic organs, we selected the discoidal IL4-aNP formulation for further studies in non-human primates and translational models of inflammation and sepsis." (PMID 37291433, 2023). "Consistent with adult studies, children with hyperferritinemic sepsis had a hypercytokinemia profile reflective of macrophage activation without a commensurate Th2 response (low IL-4 and IL-13)." (PMID 37674218, 2023). "Interestingly, IL-4 and IL-13 signaling was also persistently upregulated in non-survivors; this could be reflective of a transition towards Type-2 immunity, which could occur during increased pathogen burden and is associated with poor outcomes in sepsis." (PMID 37822940, 2023). "Interleukin-6, interleukin-2, interleukin-4 and procalcitonin in KD with severe sepsis group were significantly higher than those in KD with non-severe sepsis group." (PMID 37234775, 2023). "LFM-A13 also reduced the histopathological changes and cellular apoptosis in intestinal tissues, inhibited the inflammatory cytokines IL-4, IL-6, and TNF-α in serum and intestinal tissues, and significantly inhibited the increase in intestinal MPO activity induced by burn sepsis." (PMID 35280898, 2022). "In contrast, the levels of TNF-α, IL-12p40, IFN-α, IFN-γ, IL-17, and IL-4 in the sepsis patients were not significantly different from those in the healthy controls." (PMID 32826331, 2020). "Moreover, we show that IL-33 induces the expansion of ILC2 populations and the subsequent production of IL-4 and IL13, which together with IL-33 induce a pronounced macrophage reprogramming toward an M2-like phenotype in sepsis-surviving mice." (PMID 28374774, 2017). "Although sepsis-surviving Il1rl1−/− mice had higher production of IL-33 than WT mice, they failed to produce more IL-4 and IL-13 in the lungs compared to the naive control mice at day 15 after CLP." (PMID 28374774, 2017). "Nevertheless, we observed an increasing production of type 2 cytokines (IL-4 and IL-13) and IL-33 in the lung tissue homogenates and bronchial lavage (BAL) fluids of sepsis-surviving mice at later time points, starting at day 3 after CLP and remaining elevated over the course of observation." (PMID 28374774, 2017).
Sepsis (continued). "Accordingly, IL-4 stimulation induced higher STAT6 phosphorylation in peritoneal macrophages from sepsis-surviving WT mice than that observed in the macrophages from naive mice, an effect that was abrogated in macrophages from sepsis-surviving Il1rl1−/− mice." (PMID 28374774, 2017). "The levels of the anti-inflammatory cytokines IL-4 and IL-10 as well as the components of innate immunity C-RP and SC5b-9 were high during sepsis in both gestational age groups, unlike the proinflammatory cytokines." (PMID 27293317, 2016). "The anti-inflammatory cytokines IL-4 and IL-10 were elevated in 8/11 PT infants with sepsis and in 7/12 VPT infants with sepsis (P > 0.05, χ2 test), resulting in 15/23 identified infants with sepsis." (PMID 27293317, 2016). "IL4 and IL13 are anti-inflammatory cytokine that increase in sepsis and may play important roles in immune regulation." (PMID 26064774, 2015). "Therefore, we investigated blood IL-1β, IL-6, IL-4, IL-5, IL-10 and IFN-γ, which play important roles in sepsis." (PMID 26586517, 2015). "The distribution of haplotype of the TGF-β, TNF-α, IL-2, IL-4, IL-6 and IL-10 genes were studied in patients with sepsis and non-sepsis." (PMID 26561011, 2015). "Nonetheless, IL-4 plasma levels of septic patients on the day of hospital admission were not different between the patients who survived and those who did not survive sepsis." (PMID 25614712, 2014). "Unexpectedly, concentrations of IL-4 were not statistically different between groups regarding secondary sepsis, severity, and outcome." (PMID 24371374, 2013). "No significant changes were observed in IL-1β, IL-2, IL-4, IL-13, GM-CSF, FGFbasic or GM-CSF in caPI3K Tg mice in the presence or absence of sepsis (data not shown)." (PMID 23028587, 2012). "In our model, septic DM mice exhibited trends toward elevated levels of pro‐inflammatory markers, including IL‐12B, CXCL‐1, and TNF‐α, and reduced IL‐4 levels compared to mice with sepsis or DM alone; however, these differences did not consistently reach statistical significance." (PMID 40654181, 2025). "Notably, the IL-2/IL-4 ratio on day +7 in patients with aGVHD showed minimal change, regardless of sepsis presence." (PMID 40718494, 2025). "In addition, anti‐inflammatory mediators, such as IL4 and IL10, are also released during sepsis, a process that not only suppresses the proinflammatory cascade but also leads to a state of relative immunosuppression in patients with sepsis." (PMID 37060578, 2023). "In the sepsis 24 h group, the production of IFN-γ was increased compared with that in the sham group, while no significant changes were observed in IL-4 levels, followed by an elevated ratio of IFN-γ/IL-4, thus indicating the dominant differentiation of Th1 subtypes." (PMID 34512319, 2021). "These IL-4-mediated changes are important for resolution of nonseptic inflammation but may actually contribute to the pathobiology of sepsis." (PMID 32676795, 2020). "In the CLP-induced sepsis, calcium-sensing receptor activation promotes T cell apoptosis and the secretion of the proinflammatory cytokine TNF-α and the anti-inflammatory cytokine IL-4 probably through NF-κB and partial ERK and JNK signal transduction pathways." (PMID 32908632, 2020). "Results indicated that neutralization of IL-4 did not improve sepsis mortality in CD43-/- hosts." (PMID 30226896, 2018). "Importantly, depleting CD25+ Foxp3+ Treg erased the observed difference in mortality between WT and CD43-/- mice, while neutralizing IL-4 or adding back IFN-g-secreting Th1-like cells had no impact on sepsis survival in CD43-/- hosts." (PMID 30226896, 2018). "This along with the present finding of highly induced Wnt5A expression in IL-4-activated VEC prompt further studies to investigate if Wnt5A contributes to vascular leakage and edema formation in severe systemic inflammatory diseases like sepsis/septic shock, and in IL-4 driven allergic inflammation." (PMID 28717346, 2017).